EGFR (epidermal growth factor receptor)
Diseases named in the same sentence as EGFR in open-access papers (continued):
Sharing a sentence is not in itself a finding about the gene and the disease.
cancer (continued). "The ERBB receptor tyrosine kinase family consists of four receptors: epidermal growth factor receptor (EGFR), human EGFR 2 (HER2), HER3, and HER4, which activate oncogenic pathways by homo- or heterodimerization in many types of cancers." (PMID 34203351, 2021). "In many cancers including OSCC, altered epidermal growth factor receptor (EGFR/ErbB1/HER1) levels contribute to tumorigenesis, metastasis and resistance to therapies, and are linked to poor rate of patient survival." (PMID 33889303, 2021). "These modifications are mainly evident in genes involved in cancer critical pathways, such as autophagy, apoptosis, EGFR (Epidermal Growth Factor Receptor) signaling, and metastasis." (PMID 34681716, 2021). "EGFR pathway is the most common therapeutic target in NSCLC, and the status of EGFR pathway revealed the viability of cancer cells." (PMID 33634993, 2021). "Three different cancer cell lines A431, HT-29 and MCF-7 were evaluated for EGFR expression by flow cytometry and found to be high, medium and low EGFR expressing cells, respectively." (PMID 33686177, 2021). "The human ErbB3 receptor confers resistance to the pharmacological inhibition of EGFR and HER2 receptor tyrosine kinases in cancer, which makes it an important therapeutic target." (PMID 34572289, 2021). "For these reasons EGFR and its preferred heterodimer partner, HER2/ERBB2, became popular targets of anti-cancer therapies." (PMID 34206026, 2021). "Different antibodies, like Trastuzumab, Pertuzumab (anti-HER2), Matuzumab (anti-EGFR) can all be respectively fused with MICA and used together as a cocktail, so that multiple antigens in cancer can be targeted at the same time." (PMID 34077462, 2021). "Such NLCs were used for the delivery of the anticancer drug paclitaxel (PTX), the EGFR TK inhibitor gefitinib (GEF), a cancer cell-targeting moiety (LHRH), an imaging agent (rhodamine), and siRNA targeted to mRNA encoding EGF receptors." (PMID 34371754, 2021). "Cetuximab selectively binds to EGFR and competitively inhibits the binding of EGF and other ligands, preventing its activation, eventually inhibiting the growth of cancer cells and production of MMP and EGF and inducing apoptosis." (PMID 33946823, 2021). "Whereas a reduction of EGFR protein level can lead to cell death in cancer cells, inhibition of tyrosine kinase activity via TKI treatment does not, suggesting the presence of tyrosine kinase-independent actions of EGFR." (PMID 34477203, 2021). "After confirming that silibinin has the capacity to suppress cancer hallmarks and CSC formation, the molecular signaling behind these mechanisms was also checked by starting from its binding to EGFR." (PMID 34209829, 2021). "These ncRNAs interact with PI3K/Akt, NF-κB, Wnt/β-catenin, EGFR, TGF-β and other cancer-related pathways." (PMID 34367998, 2021). "EGFR is one of the most important targets of antitumor therapy, and EGFR antagonists may eventually play an indispensable clinical role not only in the treatment of malignant tumors but also in the treatment of pain, especially cancer pain, which is resistant to opioid treatment." (PMID 34520454, 2021). "Owing to existing EGFR-targeted drugs, EGFR would be a potential target for HPV-induced cancer prognosis improvement." (PMID 34646755, 2021). "Among cancer‐critical genes (defined in the COSMIC Cancer Gene Census), recurrent high‐level amplifications were found only of ERBB2 in two patients, while EGFR and the cell cycle genes CDK6, CCND2, and CCND3 were amplified in one patient each." (PMID 33325154, 2021). "In oral SCC cells, downregulation of leucine-rich repeats and immunoglobulin-like domains 1 (LRIG1) induced the activation of EGFR-mediated SphK1 signaling to promote extracellular matrix (ECM) remodeling and cancer cell progression." (PMID 33465049, 2021). "Lawan AI and co-workers explored the expression of EGFR in 54 patients with CRC carcinoma and reported that EGFR was expressed in 85.2% of the cancer cases." (PMID 34638601, 2021).
cancer (continued). "Other techniques using RT-PCR focusing on different cancer-specific genes, such as CK20, UPII, and EGFR, have also been described." (PMID 33922894, 2021). "ImmunoPET has been used for in vivo imaging of cancer-specific markers, such as HER2 and EGFR 20,56." (PMID 33391977, 2021). "AGK in prostate cancer cells increases the formation and secretion of LPA, which leads to the transactivation of EGFR and the activation of the downstream MAPK signaling pathway, resulting in the growth of cancer cells." (PMID 34368119, 2021). "Treatment with compound 1 inhibited the EGFR/AKT pathway and induced cell cycle arrest and apoptosis in both cancer cell types." (PMID 34279406, 2021). "The selective cytotoxicity of PLU is due to its ability to regulate multiple cancer signaling pathways, such as FZD–Wnt, EGFR, and NF-κB signaling." (PMID 34202294, 2021). "Additional guanine nucleotide exchange factors (GEFs) mediate the effects of EGFR and RAC1 on cancer cell migration." (PMID 34206026, 2021). "The cancer genome atlas (TCGA) analysis showed that the ZNF516 gene is highly expressed in certain cancer types and is a potential suppressor of EGFR, which is related to breast carcinogenesis." (PMID 33750298, 2021). "EGFR and DPAGT1 were expressed on the cancer cell surface (arrowheads in d and merge e) and in the perinuclear area (arrowheads in g and merge h), respectively." (PMID 32901097, 2021). "Ibrutinib represses the phosphorylation of EGFR and thus inhibits the downstream activation of AKT and ERK signaling in these cancer cells, leading to reduced tumorigenicity both in vitro and in vivo." (PMID 34778053, 2021). "This demonstrated that the anti-EGFR antibody targeted AuNRs were internalised strongly by KYSE-30 and CAL-27 cancer cells compared with the Hep G2 and MCF-7 cancer cell lines." (PMID 34683944, 2021). "Thus, we hypothesized that other HPV(+) cancer cell lines would remain EGFR-signaling dependent." (PMID 33481911, 2021). "KRIBB11 effectively decreased the HSP70/BAG3/BCL2 and EGFR/MET/AXL proteins, leading to apoptosis of resistant cancer cells." (PMID 34203709, 2021). "Both EGFR and VEGFR2 regulate downstream PI3 K/AKT and MAPK signaling pathways in cancer cells that co-express both EGFR and VEGFR2." (PMID 33804477, 2021). "Mechanistically, through directly interacting with miR-491-5p, circ_CELF1 acted as a miRNA sponge that increased the expression of the miR-491-5p target gene EGFR, eventually promoting the progression of NSCLC and increasing cancer resistance to immunotherapy." (PMID 34788230, 2021). "Modern molecular imaging modalities currently in use for the detection of EGFR- and VEGFR-overexpressed cancers include PET, SPECT, CT, MRI, US, and OI." (PMID 33670650, 2021). "Expression increase of VEGFA, PGE2S, COX2, EGFR, and NANOG in cancer cells was characteristic for the increase of resistance, as the sensitizing ratio was the opposite in the principal component analysis." (PMID 33671869, 2021). "Deletion of J2R and C11R allows for vvDD to selectively replicate in cells with an active E2F and epidermal growth factor receptor (EGFR/Ras) pathway, common features of many cancer cells." (PMID 33924556, 2021). "TSG101, an ESCRT-I protein, played extensive roles in modulating cell proliferation, apoptosis, actin remodeling, and EGFR and JAK/STAT in cancers." (PMID 33959493, 2021). "Prostaglandin G/H synthase 2 (PTGS2) exhibits the highest degree and regulates 13 types of cancers, followed by HSP90AA1 (degree = 12), EGFR (degree = 12), and MMP2 (degree = 11)." (PMID 34248628, 2021). "ErbB3 is a member of EGFR family of receptor tyrosine kinases, which serves as a homolog to EGFR (ErbB1) and HER2 (ErbB2) and plays an important role in cancers." (PMID 34400880, 2021).
cancer (continued). "Mechanistically, they show that cancer cells treated with TKIs targeting MET and EGFR secrete higher levels of lactate, which then instructs CAFs to secrete HGF, resulting in the non-responsiveness of cancer cells to the treatment." (PMID 34298736, 2021). "EGFR activation is partly due to α2,6 sialylation of the EGFR by ST6Gal1, which affects EGF-induced cancer cell proliferation." (PMID 33827580, 2021). "Amplification of EGFR is a most prevalent aberration in GBM, as well as in carcinomas of the breast, colorectum, and lung." (PMID 34206026, 2021). "Among these GFRs, the epidermal growth factor receptor (EGFR) and hepatocyte growth factor receptor (HGFR) play central roles in the pathogenesis and progression of different carcinoma types." (PMID 34512327, 2021). "NEDD4L level is significantly changed, and it exhibits distinct functions in different carcinomas by regulating certain major pathways (such as TGF-β, WNT and EGFR signaling pathways)." (PMID 37305161, 2021). "In EGFR-overexpressing carcinoma cells, we found that the Src family kinase (SFK) inhibitor PP2 reduces β4 tyrosine phosphorylation following the activation of EGFR." (PMID 33883672, 2021). "In addition, a part of SNSCC non- and keratinizing with no documented ISP simultaneously to carcinoma or in patient’s history showed EGFR mutations, while none of the other carcinoma types were EGFR mutated, indicating a common origin of tumors with the EGFR mutation." (PMID 34885191, 2021). "Afterwards, Abdelsalam and co-workers designed some benzo[h]quinoline derivatives, as molecule 55, with good anticancer activity against MCF-7 cancer cell line (IC50 = 7.21 ± 0.43 μM) and also an EGFR IC50 = 0.14 μM." (PMID 32961977, 2020). "We confirmed that iBET-151 reduced the expression of RTK mRNA and proteins, including EGFR, ERBB3, MET, and IGF-1R, thereby regulating cancer cell growth and survival." (PMID 33412753, 2020). "Known cancer genes such as EGFR, EZH2, or CCDN2 were frequently affected by duplications and other known cancer genes such as CDKN2A, RB1, KLK2, or CD79A were frequently affected by deletions." (PMID 32604718, 2020). "Survivin, a prosurvival factor, promoted the resistance against EGFR-TKIs and decreased survivin expression by inhibiting PI3K-Akt signaling pathway and enhanced the chemosensitivity of cancer stem cells to EGFR-TLIs." (PMID 32256584, 2020). "The gene set enrichment analysis revealed that these interacting proteins also interacted with cancer-related proteins, including KISS1, TIMP2, MMP11, IGFBP1, EGFR, and CDKN1C." (PMID 32117443, 2020). "Tyrosine kinase inhibitors, such as erlotinib, inhibit EGFR activation and have anti-cancer effects, although CCA tumors often have resistance to EGFR inhibitors." (PMID 32069926, 2020). "EGFR also binds FAK via SRC-3Δ4 adaptor molecule and phosphorylates it at Y925 to promote cancer cell migration and invasion." (PMID 32719793, 2020). "As the EGFR pathway plays important roles in metastasis of cancer, we confirmed the role of the EGFR pathway in cir-ITCH-inducedmetastasis by the addition of EGFR activator and inhibitor." (PMID 31960764, 2020). "As with the continued clinical development of BRAF inhibition in BRAF mutant cancers, the activity of PLX8394 should be investigated as part of a combination with other drugs that limit pathway reactivation such as MEK and EGFR inhibitors." (PMID 32922659, 2020). "It increases the translation of certain mRNA, including epidermal growth factor receptor (EGFR) and the Hippo pathway effector TAZ in human cancer cells." (PMID 32258108, 2020). "The study of the biology of cancer identified many oncogenes such as the transcription factor c-myc, the regulatory GTP-binding protein Ras, and the receptor tyrosine kinase epidermal growth factor receptor (EGFR)." (PMID 32577154, 2020).
cancer (continued). "Using the CCLE data, a gene-centric integration in each cluster accurately identified known drivers in several cancer types, including MITF in melanoma, ERBB2 in breast cancer, EGFR and MET in LUAD, and MYCN in brain tumors." (PMID 32076369, 2020). "Epithelial–mesenchymal transition (EMT) is an important event in promoting cancer metastasis and determining the sensitivity of NSCLC to EGFR TKI." (PMID 33126605, 2020). "EGFR is known to crosstalk with various receptor systems including integrins and platelet-derived growth factor receptor (PDGFR), and thus contributes to cancer malignancy." (PMID 33092268, 2020). "Without expression of these proteoglycans, there is decreased regulation of several established and potent oncogenic pathways such as EGFR, TGFβ, MYC, and c-MET that can lead to cancer growth and metastasis." (PMID 32553107, 2020). "Studies have shown that IL-6, EGFR, NOTCH and TGF-β1 form an oncogenic signal network in cancer initiation and progression." (PMID 32894152, 2020). "We have demonstrated that phosphorylation of multiple RTKs, such as EGFR, FGFR2, IGF1R, and MET, can be regulated by O-glycosylation in various cancers." (PMID 32005975, 2020). "It interacted with some epidermal growth factor receptor (EGFR), human epidermal growth factor receptor-2 (HER2), which played an important role in cancer pathway and participates in various pathophysiological processes of cells." (PMID 31949263, 2020). "A growing evidence indicate that downregulation of Sp1 and Sp3 expressions by drugs or RNA interference can induce autophagy by depressing EGFR activity and downstream the AKT/MAPK pathways in cancer cells 20,36." (PMID 32226300, 2020). "HSP90 family chaperones were most often discussed in the context of cancer as some of HSP90’s known substrates are oncogenic protein kinases such as SRC, FAK, MET, EGFR, HER2 as well as the telomerase and the other main oncogenic drivers." (PMID 32545208, 2020). "Slow cycling cancer cells are enriched by anti-cancer drugs and confer resistance by activating various signaling pathways, including the WNT5A and EGFR pathways." (PMID 32626712, 2020). "The mechanisms of Sora resistance remain obscure, but new insights include a higher EGFR, c-Jun and Akt activation in HCC cells, as well as increased EMT, cancer stem cells, hypoxic environment, autophagy, and exosomes." (PMID 32000827, 2020). "We show that the SWIR fluorescence imaging using ICG–antibody conjugates can be used for the elucidation of expression level of cancer-specific membrane proteins, HER2, EGFR, VEGFR-2, and PD-L1 in vivo." (PMID 35519107, 2020). "As we are only interested in genetic vulnerabilities unique to cancer cells, we also performed differential essentiality analysis comparing NCI-H1650 with EGFR wild-type cell lines to filter out vulnerabilities that would also kill healthy tissue." (PMID 33205120, 2020). "Currently inhibitors of cell surface receptors or upstream kinases such as EGFR and BRAF are used as target therapy in various types of cancer and accomplish remarkable improvement in cancer treatment." (PMID 33172112, 2020). "For instance, G-Rh2 induces the apoptosis of cancer cells by inhibiting FGFR2, CSF1R, EGFR, and LYN." (PMID 33488754, 2020). "In cancer cells, YB-1 has been shown to activate the expression of several genes important for cell proliferation, such as DNA polymerase α, cyclins, PIK3CA, EGFR and HER-2, with some of these molecules being implicated in trophoblast proliferation." (PMID 32842598, 2020).
cancer (continued). "Neuropilin-1 (NRP1) is a transmembrane receptor that promotes the progression of cancer by interacting with VEGF/VEGFR2 and EGFR." (PMID 32708604, 2020). "In these studies, epidermal growth factor receptor (EGFR), HER2, and the cancer stem cell marker CD133 stood out as promising targets for further development of PCI enhanced targeted toxins." (PMID 32075165, 2020). "Cetuximab, a therapeutic antibody that blocks the function of epidermal growth factor receptor, induced apoptosis and autophagy, and the knockdown of ATG7 or Beclin1 or treatment with CQ sensitized cancer cells to cetuximab-triggered apoptosis." (PMID 33239065, 2020). "These are the reasons that the EGFR cascade and particularly BRAF oncogene has become of interest in various research searching for novel cancer treatments." (PMID 33247675, 2020). "We demonstrated that EGFR activation contributes to innate resistance to prexasertib in TNBC and potentially other cancers." (PMID 35582228, 2020). "This novel review discusses the role of the activation of EGFR, Wnt/β-catenin, Hippo, TGF-β, and JAK/STAT cascades in CAFs in relation to the chemoresistance and invasive/metastatic behavior of cancer cells." (PMID 32546182, 2020). "Several approaches, including the development of antibodies and small molecule inhibitors, have been employed to target EGFR and HER2 receptors or EGFR/HER2-modulated effects for cancer therapy 8-11." (PMID 32398965, 2020). "Two critical members of the EGFR signaling pathway are MEK and ERK, which play an important role in cancer progression and chemoresistance." (PMID 32231055, 2020). "Previous studies indicated that ADAM9 mediates cancer progression via regulating epithelial-to-mesenchymal transition (EMT), shedding EGFR ligands, and activating EGFR/AKT signaling pathway." (PMID 32637415, 2020). "Cancer with bone metastasis showed estrogen receptor and SNAI1 over-expression; cancer with liver metastasis showed SNAI1 over-expression; and cancer with lung metastasis showed EGFR, CK5 and HER2 protein over-expression." (PMID 33369456, 2020). "In this context, the epidermal growth factor receptor (EGFR) is a promising target for PS-immunoconjugates, considering it is commonly overexpressed in cancer cells." (PMID 33552982, 2020). "Collectively, we aimed to investigate the correlation between EGFR, mitochondrial metabolism and tumorigenesis and to delineate the differences in energy metabolism between TKI-sensitive cancer cells and TKI-resistant cancer cells." (PMID 31936895, 2020). "EGFR and downstream molecules such as AKT and ERK activate many biological outputs that are beneficial to cancer cell proliferation and progression through the cell cycle." (PMID 33369441, 2020). "Slow internalization (less than 30% activity internalized by cancer cells within 24 h in vitro) was found for monomeric forms of affibody molecules binding HER2, EGFR, HER3, and CAIX." (PMID 32168760, 2020). "We additionally elucidated the crosstalk among the EGFR–ERK signaling, ILF3 expression level, and the SGOC network during cancer formation." (PMID 31772275, 2020). "We studied the interactions of MET and EGFR upon stimulation by HGF or EGF in the two cancer cell lines, HeLa and BT-20, which exhibit inverse MET:EGFR expression ratios." (PMID 32316583, 2020). "Therefore, the EGFR signaling pathway could be an attractive target for cancer therapy." (PMID 32328181, 2020). "To further examine the complement activation mediated by EGFR inhibition on cancer cells, we focused on cell line HN5 with prominent complement activation after EGFR inhibition." (PMID 32054454, 2020). "At present, many oncogenes are known to induce or promote the metastatic potential of HCC cells, such as Ras, Myc, Raf, Fos, EGFR, and c-Met, while KAI1 and PTEN can inhibit the metastasis and recurrence of cancer." (PMID 33123581, 2020).